MIR155HG (MIR155 host gene)
Description:
Negatively regulates MHC class II antigen presentation in dendritic cells by interacting with the molecular chaperone HSPA8 and impairing its role in lysosomal antigen transport. Does not regulate the levels or activity of the MIR155HG microRNA from which miPEP155 is derived.
Synonyms: BIC; BIC-155; miPEP155; NCRNA00172; LncRNA-SERB; MIRHG2
Gene: Long non-coding RNA gene on chromosome 21 (25,560,592 to 25,575,168, forward strand). Ensembl gene ENSG00000234883.
Subcellular location: Cytoplasm; Nucleus
Gene Ontology:
Biological process: miRNA-mediated post-transcriptional gene silencing
Cellular component: RISC complex
Diseases named in the same sentence as MIR155HG in open-access papers:
MIR155HG is named in the same sentence as 40 diseases in open-access papers, as found by Europe PMC text mining. Sharing a sentence is not in itself a finding about the gene and the disease. The quoted sentences say what the papers report.
glioma (9 papers, 2020 to 2024). A benign or malignant brain and spinal cord tumor that arises from glial cells (astrocytes, oligodendrocytes, ependymal cells). "MIR155HG has also been implicated in promoting malignant phenotypes that enhance glioma immune evasion." (PMID 37403043, 2023). "MIR155HG has been found to be positively associated with tumor grade and represents an independent adverse prognostic factor in glioma patients." (PMID 37403043, 2023). "We also detected significant downregulation of MIR155HG, whose high expression is associated with glioma progression and poor survival." (PMID 32488114, 2020). "MIR155HG is associated with poor prognosis and tumor progression in glioma and pancreatic cancer." (PMID 38339237, 2024). "Studies have shown high MIR155HG expression levels in lymphomas 15-17, leukemia 18, gliomas 19-21, and non-small-cell lung cancer 22, and MIR155HG functions as an oncogene in these cancers." (PMID 37324190, 2023). "The expression of MIR155HG has been found to be positively correlated with tumor grade and prognosis of glioma patients." (PMID 33750353, 2021). "Finally, five lncRNAs (CYTOR, MIR155HG, LINC00641, AC120036.4 and PWAR6) were chosen to establish a risk score system for prediction the prognosis of gliomas." (PMID 33750353, 2021). "Knockdown of MIR155HG by inhibiting the Wnt/β-catenin pathway via downregulation PTBP1 could increase glioma sensitivity to TMZ." (PMID 34178658, 2021). "Consistent with previous research findings, the other 7 lncRNAs that we have identified in our risk model, have all been reported to play significant biological roles in gliomas, particularly HOXA-AS3, LINC00665, MIR155HG, and NEAT1." (PMID 37403043, 2023). "In comparison with expression levels of lncRNAs in low grade glioma, CYTOR and MIR155HG were significantly over-expressed in GBM tissues, while three lncRNAs (LINC00641, AC120036.4, PWAR6) were remarkably down-regulated in GBM samples." (PMID 33750353, 2021). "In the TCGA, CGGA and Our datasets, differential expression analysis showed that CYTOR and MIR155HG were significantly overexpressed in GBM compared to LGG samples, while AC120036.4, LINC00641 and PWAR6 showed an inverse expression pattern in glioma samples." (PMID 33750353, 2021). "Through qRT-PCR, we confirmed that AP001007.1, MIR155HG, and LBX2-AS1 are highly expressed, while LINC00515 and MAPT-AS1 are low expressed in gliomas compared to the control group." (PMID 33391355, 2020). "Furthermore, we examined the expression of the signature lncRNAs in cell lines U251 and T98G as tumor group, SVGp12 as normal or control group, by qPCR analysis, showing that the expression of CPB2-AS1, MIR155HG, LINC00906 and WDR11-AS1 were low in gliomas cells." (PMID 37153654, 2023).
cervical cancer (5 papers, 2021 to 2025). A primary or metastatic malignant neoplasm involving the cervix. "MIR155HG was shown to be significantly upregulated in cervical cancer patients, and propofol reduced the expression of MIR155HG, thereby inhibiting the growth and invasion of cervical cancer cells, and this effect was confirmed both in vivo and in vitro." (PMID 40309242, 2025). "Herein, we also found that knockdown of MIR155HG lessened the expression of N-cadherin and raised the expression E-cadherin in cervical cancer cells, indicating that knockdown of MIR155HG effectively suppressed EMT progression in cervical carcinoma cells." (PMID 34775376, 2021). "Consistently, the results from in vivo xenograft model indicated that propofol repressed cervical cancer cells growth and decreased the expression of MIR155HG in vivo." (PMID 34775376, 2021). "MIR155HG could promote the migration and invasion of cervical cancer cells, and MIR155HG knockdown suppresses cell proliferation, migration, and invasion in non-small cell lung cancer." (PMID 36333764, 2022). "In addition, MIR155HG was identified to be distinctly upregulated in cervical carcinoma when compared within normal." (PMID 34775376, 2021). "Notably, knockout of the MIR155HG gene resulted in the inhibition of cervical cancer cell proliferation, suggesting that MIR155HG is involved in the pathogenesis of cervical cancer and may serve as a valuable therapeutic target." (PMID 40303981, 2025).
lymphoma (5 papers, 2013 to 2023). A malignant (clonal) proliferation of B- lymphocytes or T- lymphocytes which involves the lymph nodes, bone marrow and/or extranodal sites. "The involvement of PKC in the regulation of Mir155hg expression has previously been reported in lymphoma cells, though the PKC isoform involved was not identified." (PMID 36538560, 2022).
breast carcinoma (4 papers, 2016 to 2026). "We found that in the regulatory network, miR-301a-3p, miR-93-5p, miR-454-3p, miR-181b-5p, XIST, LINC00472, MIR31HG, MEG3, MIR155HG, and LINC00667 have been reported in breast cancer." (PMID 34220926, 2021). "Another study showed how the NF-κB pathway plays a role in enhancing stemness and radioresistance in breast cancer stem cells (BCSCs) by regulating MIR155HG, a long non-coding RNA MIR155 host gene (MIR155HG) located on human chromosome 21, via transcriptionally activating the Wnt pathway." (PMID 41305005, 2025). "For example, in a study of 51 human breast cancer cell lines, MIR22HG and MIR155HG are demonstrated to be significantly higher expressed in normal-like cells and basal-like cells respectively." (PMID 27634900, 2016).
B cell lymphoma (3 papers, 2021 to 2024). "The LncRNA-SERB (ENST00000456917), also named as MIR155 host gene (MIR155HG), which can be transcriptionally activated by promoter insertion at a common retroviral integration site in B-cell lymphomas." (PMID 38641065, 2024). "In agreement with this, MIR155HG was recently reported to encode a 17-amino acid micropeptide named miPEP155, detected in HEK293T, OCI-LY-1 (human B cell lymphoma), and human dendritic cells." (PMID 33810468, 2021). "Multiple studies have shown that MIR155HG is highly expressed in diffuse large B-cell (DLBC) lymphoma and primary mediastinal B-cell lymphoma, and in chronic lymphocytic leukemia." (PMID 38741200, 2024).
chronic obstructive pulmonary disease (3 papers, 2022 to 2024). A chronic and progressive lung disorder characterized by the loss of elasticity of the bronchial tree and the air sacs, destruction of the air sacs wall, thickening of the bronchial wall, and mucous accumulation in the bronchial tree. "Our data show an upregulation of the well know inflammation-related miR-155 as well as its host gene MIR155HG, which is involved in pro-inflammatory response during chronic obstructive pulmonary disease and against influenza A virus." (PMID 36685903, 2022).
gastric cancer (3 papers, 2023 to 2024). A primary or metastatic malignant neoplasm involving the stomach. "Overexpression of MIR155HG promotes gastric cancer proliferation, migration, and chemoresistance via NF-B and STAT3 (signal transducer and activator of transcription 3) signaling pathways." (PMID 38339237, 2024). "Studies have shown that MIR155 host gene (MIR155HG) acts as an oncogene in several cancers, but the function and its mechanism of MIR155HG in gastric cancer (GC) is still poorly understood." (PMID 37324190, 2023). "It has been reported that MIR155HG promotes the migration and invasion of gastric cancer cells." (PMID 38693854, 2024).
melanoma (3 papers, 2022 to 2023). A malignant, usually aggressive tumor composed of atypical, neoplastic melanocytes. "On the other hand, high expression level of MIR155HG gene is significantly associated with better survival in human melanoma patients indicating its potential role as a tsmiRNA." (PMID 37409119, 2023). "Likewise, increased expression of MIR155HG is directly linked to the heightened expression of immune checkpoint genes in melanoma, potentially compromising the effectiveness of melanoma immunotherapies." (PMID 37629553, 2023). "Finally, MIR155HG, located on chromosome 21, encodes a microRNA, miR-155, was chosen because linked to cell proliferation and cancer, including in melanoma where it is downregulated." (PMID 36125262, 2022).
glioblastoma (2 papers, 2023 to 2024). The most malignant astrocytic tumor (WHO grade IV). "Using this strategy, 29 essential ER lncRNAs were prioritized, of which 7 were reported to be associated with immune regulation and glioblastoma therapy from previous studies (i.e. PVT1, MIR155HG, and LINC00346)." (PMID 37056564, 2023).
leukemia (2 papers, 2023 to 2024). A malignant (clonal) hematologic disorder, involving hematopoietic stem cells and characterized by the presence of primitive or atypical myeloid or lymphoid cells in the bone marrow and the blood. "MYB physically binds to the promoter of the miR-155 host gene (MIR155HG) and stimulates its transcription, which leads to leukemia." (PMID 39758420, 2024).
lung adenocarcinoma (2 papers, 2024). A carcinoma that arises from the lung and is characterized by the presence of malignant glandular epithelial cells. "Previous studies revealed that MIR155HG possessed an oncogenic role in many types of tumors including lung adenocarcinoma (LUAD), along with higher expression in tumors." (PMID 39043648, 2024). "Therefore, we have unraveled the molecular mechanism of MIR155HG regulation in tumors and discovered a biomarker of immunotherapy efficacy in lung adenocarcinoma and a combination treatment strategy." (PMID 39043648, 2024). "We initially investigated TCGA datasets of lung adenocarcinoma (LUAD) and GEO dataset (GSE40791), which revealed that MIR155HG expression in LUAD was markedly higher than that in adjacent normal tissues, which was confirmed in a small LUAD cohort with 30 paired samples." (PMID 39043648, 2024).
pulpitis (2 papers, 2021 to 2023). Inflammation of the dental pulp. "Three lncRNAs (i.e., XIST, MIR155HG, and LINC00630) are identified to be key factors involved in the ceRNA network of pulpitis." (PMID 33777260, 2021).
atherosclerosis (1 paper, 2023). A disease characterized by the build-up of fatty material and calcium deposition in the arterial wall resulting in partial or complete occlusion of the arterial lumen. "Molecular docking revealed most DSY bioactive components can bind key EndMT-related lncRNAs, including AC003092.1, MIR181A1HG, MIR155HG, WEE2-AS1, and MIR137HG, suggesting DSY may mitigate EndMT in atherosclerosis by modulating the ceRNA network." (PMID 38268851, 2023).
Autoimmunity (1 paper, 2024). The occurrence of an immune reaction against the organism's own cells or tissues. "We reported that human MIR155HG encodes miPEP155 that suppresses antigen presentation in dendritic cells during autoimmunity; mouse mir31hg encodes miPEP31 that acts as a transcriptional repressor, inhibiting the expression of the pro-inflammatory miRNA-31." (PMID 38291338, 2024).
colorectal cancer (1 paper, 2024). A primary or metastatic malignant neoplasm that affects the colon or rectum. "MIR155HG promotes M2 macrophage polarization and tumor progression and enhances oxaliplatin resistance in colorectal cancer cells via the miR-650/ANXA2 axis." (PMID 38339237, 2024).
depression (1 paper, 2022). "MIR155HG was also shown to repress miR-155, and MIR155HG overexpression ameliorates depression-like behaviors within mice." (PMID 35955886, 2022).
laryngeal carcinoma (1 paper, 2024). Carcinoma that arises from the laryngeal epithelium. "Furthermore, MIR155HG is overexpressed in tissue samples of laryngeal cancer, and its high expression is associated with lymph node metastasis and advanced tumor stage." (PMID 38339237, 2024).
laryngeal squamous cell carcinoma (1 paper, 2024). A squamous cell carcinoma that arises from the larynx. "Furthermore, MIR155HG and miR-155-5p are upregulated by transforming growth factor β (TGF-β) induction, which subsequently promotes the progression and EMT of laryngeal squamous cell carcinoma." (PMID 38339237, 2024).
lung carcinoma (1 paper, 2021). "Similarly, the expression of MIR155HG was found to be significantly (P-value = 0.019) associated with the overall survival of lung cancer." (PMID 34262591, 2021).
ocular toxoplasmosis (1 paper, 2019). Ocular toxoplasmosis is an infection in the eye caused by the parasite, Toxoplasm a gondii. "In our results—obtained in human retinal Müller cells, which have direct relevance to ocular toxoplasmosis—LINC01105, BANCR, MIR17HG, MIR155HG, lnc-SGK1, MEG3, KCNQ1OT1, NEAT1, NeST, and MALAT1 were the most dysregulated lncRNAs with known immunologic activities." (PMID 31547203, 2019).
tumor (16 papers, 2014 to 2024). "miR-155 is encoded by the MIR155 host gene (MIR155HG) and plays a critical role in various physiological and pathological processes, such as hematopoiesis, immune response, inflammation, neoplasia, and cardiovascular and metabolic diseases." (PMID 33540559, 2021). "Therefore, variants in HOTAIR and MIR155HG genes could influence their roles in regulating M1/M2 macrophage balance, as well as immune cell infiltration in the tumor microenvironment and expression of immune checkpoint molecules." (PMID 38339237, 2024). "For example, MIR155HG can regulate the tumor-immune microenvironment through cytokine‒cytokine receptor interactions and complement and coagulation cascades and is positively correlated with TIM-3 expression." (PMID 38485995, 2024). "Our study revealed that MIR155HG abrogates its intrinsic oncogenic role by inducing tumor CCL5 secretion dependent on YBX1, thus promoting the recruitment of CD8+ T cells." (PMID 39043648, 2024). "We observed significant changes in tumor growth in immunodeficient mice between MIR155HG overexpression and the control group or MIR155HG knockdown and the control, which supported the tumor intrinsic oncogenic role of MIR155HG." (PMID 39043648, 2024). "Taken together, these data suggested that the overexpression of MIR155HG in tumor cells suppresses T cell-mediated antitumor activity." (PMID 39043648, 2024). "And we found MIR155HG overexpression markedly increased the size and weight of the tumor in mice compared to the control group." (PMID 37324190, 2023). "In vitro and in vivo studies demonstrated that MIR155HG modulated the malignant phenotype of GC cells, such as cell proliferation, colony forming ability, cell migration ability, and tumor growth in nude mice." (PMID 37324190, 2023). "Similarly, propofol also significantly reduced the level of MIR155HG in tumor tissue as demonstrated by qRT-PCR assay." (PMID 34775376, 2021). "Additionally, MIR155HG, which can also competitively bind to miR-129-5p, is an important regulatory factor for hematopoietic, inflammatory, immune, and tumor development processes, as well as other physiological and pathological processes." (PMID 33579282, 2021). "MIR155HG is involved in immune infiltration and immune checkpoint molecular expression in various cancers and may be a biomarker of tumor prognosis." (PMID 32425969, 2020). "We found that MIR155HG was significantly associated with immunological checkpoint blocking molecules PD‐1, PD‐L1, CTLA4, LAG3, and TIM3 in many tumors, and some of those types of tumor have better reactivity against immunological checkpoint blockade." (PMID 31568700, 2019). "In conclusion, we have identified miR-155-3p might be a novel tumor suppressive microRNA silenced in MCL due to promoter hypermethylation of its host gene MIR155HG, resulting in upregulation of LT-β." (PMID 25211095, 2014). "Thus, MIR155HG overexpression promotes tumor growth of GC cells in vivo." (PMID 37324190, 2023). "MIR155HG gene is activated by MYB transcription factor and thus up-regulated, which in turn leaded to down-regulation of many tumor suppressor genes." (PMID 31959117, 2020). "A comparison of expression in tumour tissue (TT) and non-malignant mucosa tissue (MT) showed significant upregulation of CCAT1 and linc-ROR in TT (p < 0.001 and p = 0.001, respectively) and downregulation of ANRIL, MIR155HG and MALAT1 (p = 0.001, p = 0.010, p = 0.001, respectively)." (PMID 30205577, 2018).
cancer (13 papers, 2018 to 2024). A tumor composed of atypical neoplastic, often pleomorphic cells that invade other tissues. "While the underlying role of MIR155HG and its expression in PTC remain elusive, recent studies have shown that MIR155HG acts as an oncogene in several cancer types." (PMID 38339237, 2024). "MIR155HG has been known as the primary miRNA of miR-155 and small molecule inhibitors of the MIR155HG/miR-155 axis would be a useful anti-cancer drug." (PMID 34572448, 2021). "MIR155HG acts as an oncogene that propels malignant progression in various cancers." (PMID 39043648, 2024). "LncRNA MIR155HG was also a key hub lncRNA in all kinds of cancers." (PMID 37770497, 2023). "As the 3p strand of the miR-155 micro-RNA has recently been shown to have multiple roles in various contexts, including cancer, inflammation and bone growth, investigating the effects of pressure on miR-155-3p target genes may be useful to uncover new functions of Mir155hg in cartilage biology." (PMID 36538560, 2022).
infection (5 papers, 2014 to 2025). The state of being infected such as from the introduction of a foreign agent such as serum, vaccine, antigenic substance or organism. "Mir155hg has also been found to function independently of miR-155 for instance in infection." (PMID 36538560, 2022). "Especially, several lncRNAs that exhibited transcriptional regulation, such as GAS5, THRIL, MIR155HG, and UCA1, also displayed consistent or increased m6A methylation signals following infection." (PMID 41267684, 2025).
hematopoietic cancers (1 paper, 2013). "MIR155HG has been proposed to be a target gene for transcription factor NF-κB largely due to the positive correlation between high nuclear NF-κB activity and increased miR-155 expression following treatment with NF-κB inducers or in subsets of hematopoietic cancers." (PMID 24059932, 2013).
immune diseases (1 paper, 2021). "A similar analysis revealed that the RNAs co-expressed with MIR155HG included Kyoto encyclopedia of genes and genomes (KEGG) pathways related to immune diseases and the immune system, suggesting a role for MIR155HG in regulating the immune microenvironment." (PMID 34248988, 2021).
MIR155HG also shares sentences with these, for which no sentence is quoted: non-small cell lung carcinoma (2 papers); breast tumors (1); Burkitt lymphoma (1); cervical squamous cell carcinoma (1); cholangiocarcinoma (1); chronic lymphocytic leukemia (1); cutaneous melanoma (1); endocervical adenocarcinoma (1); infarction (1); metabolic disease (1); pancreatic cancer (1); renal clear cell carcinoma (1); Sepsis (1); Thyroid carcinoma (1); uveal melanoma (1).